USP33 (ubiquitin specific peptidase 33)
Description:
Deubiquitinating enzyme involved in various processes such as centrosome duplication, cellular migration and beta-2 adrenergic receptor/ADRB2 recycling. Involved in regulation of centrosome duplication by mediating deubiquitination of CCP110 in S and G2/M phase, leading to stabilize CCP110 during the period which centrioles duplicate and elongate. Involved in cell migration via its interaction with intracellular domain of ROBO1, leading to regulate the Slit signaling. Plays a role in commissural axon guidance cross the ventral midline of the neural tube in a Slit-dependent manner, possibly by mediating the deubiquitination of ROBO1. Acts as a regulator of G protein-coupled receptor (GPCR) signaling by mediating the deubiquitination of beta-arrestins (ARRB1 and ARRB2) and beta-2 adrenergic receptor (ADRB2). Plays a central role in ADRB2 recycling and resensitization after prolonged agonist stimulation by constitutively binding ADRB2, mediating deubiquitination of ADRB2 and inhibiting lysosomal trafficking of ADRB2. Upon dissociation, it is probably transferred to the translocated beta-arrestins, leading to beta-arrestins deubiquitination and disengagement from ADRB2. This suggests the existence of a dynamic exchange between the ADRB2 and beta-arrestins. Deubiquitinates DIO2, thereby regulating thyroid hormone regulation. Mediates deubiquitination of both 'Lys-48'- and 'Lys-63'-linked polyubiquitin chains.
Synonyms: KIAA1097; VDU1
Tractability: PROTAC: UniProt records ubiquitination sites on it; ubiquitination databases record sites on it; its protein half-life has been measured.
Target class: Enzyme; Hydrolase
Gene: Protein-coding gene on chromosome 1 (77,694,725 to 77,759,884, reverse strand). Ensembl gene ENSG00000077254.
Subcellular location: Cytoplasm, perinuclear region; Cytoplasm, cytoskeleton, microtubule organizing center, centrosome; Golgi apparatus (Isoform 3)
Subcellular location (Human Protein Atlas): Golgi apparatus; Nucleoplasm
Pathways (Reactome):
Developmental Biology: Regulation of expression of SLITs and ROBOs
Metabolism of proteins: Ub-specific processing proteases
Gene Ontology:
Molecular function: cysteine-type deubiquitinase activity; cysteine-type endopeptidase activity; G protein-coupled receptor binding; protein binding; small GTPase binding; ubiquitin binding; zinc ion binding
Biological process: centrosome duplication; positive regulation of autophagosome assembly; protein deubiquitination; protein K48-linked deubiquitination; protein K63-linked deubiquitination; protein stabilization; regulation of G protein-coupled receptor signaling pathway; axon guidance; cell migration; nervous system development; ubiquitin-dependent protein catabolic process
Cellular component: centrosome; Golgi apparatus; perinuclear region of cytoplasm; cytoplasm; cytosol; VCB complex; cell body
Genetic constraint (gnomAD): Loss-of-function variants: 38 observed, 103.83 expected, observed/expected ratio (o/e) 0.37, 90% interval 0.28 to 0.48. The upper end of that interval is the gene's LOEUF score, 0.48, which puts it in group 2 of 6, group 1 being the genes least tolerant of losing a copy. Missense variants: 786 observed, 1,006.2 expected, observed/expected ratio (o/e) 0.78, 90% interval 0.74 to 0.83. Synonymous variants: 320 observed, 337.51 expected, observed/expected ratio (o/e) 0.95, 90% interval 0.86 to 1.04.
Homologues: Orthologues: chimpanzee USP33 (99% identical), macaque USP33 (98% identical), dog USP33 (97% identical), rabbit USP33 (94% identical), rat Usp33 (93% identical), mouse Usp33 (92% identical), pig USP33 (92% identical), guinea pig USP33 (88% identical), tropical clawed frog usp33 (75% identical), zebrafish usp33 (70% identical). Paralogues in human: USP20 (60% identical), USP44 (19% identical), USP49 (18% identical), USP11 (17% identical), USP9X (17% identical), USP15 (16% identical), USP3 (16% identical), USP19 (16% identical), USP4 (16% identical), USP32 (16% identical), USP9Y (16% identical), USP24 (16% identical), and 59 more.
Diseases named in the same sentence as USP33 in open-access papers:
USP33 is named in the same sentence as 34 diseases in open-access papers, as found by Europe PMC text mining. Sharing a sentence is not in itself a finding about the gene and the disease. The quoted sentences say what the papers report.
lung carcinoma (9 papers, 2014 to 2024). "The list of diseases currently reported to be associated with the dysregulation of USP33 includes breast cancer, acute lymphoblastic leukaemia, and lung cancer." (PMID 29743814, 2018). "In this study, we show that USP33 is down-regulated in multiple cohorts of lung cancer patients and that low expression of USP33 is associated with poor prognosis." (PMID 24981056, 2014). "Our study provides, for the first time, evidence that USP33 is a lung cancer associated gene and that its expression is reduced in lung cancer tissue samples." (PMID 24981056, 2014). "We demonstrate that expression of USP33 is down-regulated in lung cancer and associated with clinical outcomes." (PMID 24981056, 2014). "With 89.5% homology between mouse and human USP33, we first demonstrated that mUSP33 could also enhance the stability of E proteins in mouse lung‐associated cells, including lung cancer cells (LLCs) and alveolar macrophages (MH‐S)." (PMID 39301916, 2024). "To test if the deubiquitinating activity of USP33 plays a role in mediating Slit activity in lung cancer cells, we used a construct of USP33 mutant that contained a point mutation, C163A, in the catalytic domain of USP33 and was capable of acting in a dominant negative fashion." (PMID 24981056, 2014). "The higher expression of USP33 is associated with better prognosis of the lung cancer patients." (PMID 24981056, 2014). "To examine the relationship between USP33 expression and the clinical outcome, we analyzed association between USP33 expression and patient survival by examining publically available microarray profiling datasets for lung cancer." (PMID 24981056, 2014). "Interestingly, four missense mutations in the catalytic domain of USP33 have been identified in lung cancer samples in the datasets from the cBioPortal for Cancer Genomics." (PMID 24981056, 2014). "miR-365a-3p enhance the migration and invasion of lung cancer cells by inhibiting ubiquitin specific peptidase 33 (USP33)/ slit guidance ligand 2 (SLIT2)/ roundabout guidance Receptor 1 (ROBO1) signaling pathway." (PMID 32595638, 2020). "Next, functional rescue assays were performed to further verify that the miR-365a-3p-mediated downregulation of USP33 promotes the proliferation, migration, and invasion of lung cancer cells." (PMID 29743814, 2018). "USP33 deubiquitinates ROBO1 in lung cancer cells to maintain its stability, thereby regulating SLIT2 activity and inhibiting cancer cell metastasis." (PMID 29743814, 2018). "On the contrary, USP33 expression is downregulated in colorectal cancer samples and multiple cohorts of lung cancer patients." (PMID 26348204, 2015). "Our results provide evidence that USP33 is a new player in lung cancer that regulates Slit-Robo signaling." (PMID 24981056, 2014). "USP33 regulates Slit signaling by stabilizing Robo1 and is required for Slit inhibition of lung cancer cell migration." (PMID 24981056, 2014). "The USP33 staining signals in the normal lung tissues showed a range from 73.33 to 300.00 (with the mean value as 198.18), whereas those in the lung cancer samples varied from 0.00 to 266.00 (with the mean value as 142.38)." (PMID 24981056, 2014). "In summary, our results showed that USP33 expression was significantly decreased in lung cancer tissues." (PMID 24981056, 2014). "For each dataset, lung cancer patients were classified into two groups based on the expression level of the USP33 gene." (PMID 24981056, 2014). "Upon down-regulation of USP33 by a specific siRNA against USP33 (siUSP33), the effect of Slit in suppressing lung cancer cell migration was abolished, indicating that USP33 is required for Slit signaling in lung cancer cells." (PMID 24981056, 2014). "Together, these results show a highly consistent pattern of down-regulation of USP33 expression in lung cancer samples." (PMID 24981056, 2014).
lung carcinoma (continued). "USP33 mRNA down-regulation was detected in 9 lung cancer cases with homozygous deletion in 2 additional cases and somatic mutations in another 9 cases." (PMID 24981056, 2014). "In this study, we demonstrate that USP33 is required for Slit inhibition of lung cancer cell migration." (PMID 24981056, 2014). "USP33 mediates Slit signaling in lung cancer cells, and this requires the enzymatic activity of USP33, because expression of USP33 mutant (C163A) abolishes the Slit activity in lung cancer cells." (PMID 24981056, 2014). "Our current work shows that in lung cancer cells, USP33 also interacts with Robo1 and is required for Slit signaling in inhibiting lung cancer cell migration." (PMID 24981056, 2014). "Remarkably, USP33 mRNA levels were significantly lower in lung cancer samples as compared with the control samples in all 5 datasets." (PMID 24981056, 2014). "In all four lung cancer datasets in which survival data are available, higher USP33 expression correlates with longer overall survival of patients." (PMID 24981056, 2014). "In the present study, our results suggest that USP33 is a critical player in lung cancer and can be a potential prognostic biomarker for lung cancer progression." (PMID 24981056, 2014). "USP33 mediates the Slit activity in inhibiting lung cancer cell migration in a manner that is dependent on its catalytic domain." (PMID 24981056, 2014). "In lung cancer cells, USP33 interacted with Robo1, similar to the observation in the breast cancer cells, as detected by co-immunoprecipitation experiments." (PMID 24981056, 2014). "Data in this study show that USP33 interacts and stabilizes Robo1 protein level in lung cancer cells by inhibiting degradation via the ubiquitin proteasome pathway." (PMID 24981056, 2014). "We first tested the involvement of USP33 in Slit inhibition of lung cancer cell migration in a wound healing assay." (PMID 24981056, 2014). "The USP33 expression levels in lung cancer samples were significantly lower than those in paired adjacent non-tumor lung tissues (P < 0.01)." (PMID 24981056, 2014). "To understand the mechanism of USP33 function in lung cancer cells, we investigated the role of USP33 in mediating Slit suppression of cancer cell migration." (PMID 24981056, 2014). "This down-regulated expression of USP33 was observed in multiple microarray datasets of lung cancer and confirmed by qRT-PCR and immunohistochemical analysis." (PMID 24981056, 2014). "Additionally, USP33 was also discovered to regulate Slit-Robo signaling pathway and inhibit tumor migration in gastric cancer, breast cancer, and lung cancer." (PMID 36582601, 2022). "In summary, we not only confirmed that miR-365a-3p targets and downregulates USP33 in lung adenocarcinoma, but we also further confirmed that miR-365a-3p promotes the proliferation, migration, and invasion of lung cancer cells by downregulating the USP33/SLIT2/ROBO1 pathway." (PMID 29743814, 2018). "Thus, in this study, we aimed to elucidate the role of miR-365a-3p in lung cancer cells and the relationship among miR-365a-3p, USP33, SLIT2, and ROBO1 in lung adenocarcinoma." (PMID 29743814, 2018). "Our data suggest that USP33 may be a candidate tumor suppressor for lung cancer with potential as a prognostic marker." (PMID 24981056, 2014). "Taken together, USP33 is a new player in lung cancer that regulates Slit-Robo signaling." (PMID 24981056, 2014). "USP33 regulates the level of Robo receptor in lung cancer cells." (PMID 24981056, 2014). "Our previous work on breast cancer and the current data from lung cancer suggest that USP33 may mediate Slit signaling in different cancer cells through different mechanisms." (PMID 24981056, 2014). "Downregulation of USP33 reduces the protein stability of Robo1 in lung cancer cells, providing a previously unknown mechanism for USP33 function in mediating Slit activity in lung cancer cells." (PMID 24981056, 2014).
lung carcinoma (continued). "Expression of the C163A-mutant USP33 abolished Slit suppression of H1299 cell migration, supporting that deubiquitinating activity of USP33 is important in mediating Slit activity in inhibiting lung cancer cell migration." (PMID 24981056, 2014). "The expression and role of USP33 in lung cancer remain unexplored." (PMID 24981056, 2014). "USP33 mediates Slit-Robo signaling in lung cancer cell migration." (PMID 24981056, 2014). "In addition, USP33 appears to have a tumor suppressor function in lung cancer because low expression of USP33 correlates strongly with poor survival of lung cancer patients." (PMID 24981056, 2014). "We asked if USP33 in lung cancer cells acted in a similar manner as in breast cancer cells." (PMID 24981056, 2014). "Data presented in this study support that USP33 may be a new tumor suppressor gene in lung cancer." (PMID 24981056, 2014). "Our elucidation of the mechanism by which miR-365a-3p mediates the USP33/SLIT2/ROBO1 signalling pathway in lung carcinogenesis thus provides a new strategy for the diagnosis and targeted therapy of lung cancer." (PMID 29743814, 2018). "The miR-365/USP33/SLIT2/ROBO1 axis, a new mechanism, was reported to inhibit the invasion and metastasis of lung cancer." (PMID 29743814, 2018). "However, the role and mechanism of USP33 in Slit signaling in lung cancer remain unknown." (PMID 24981056, 2014). "To identify new players and evaluate the potential role of USP33 in lung cancer, we measured levels of USP33 expression in a panel of lung cancer samples with the matched adjacent non-tumor lung tissue controls." (PMID 24981056, 2014). "USP33 expression was significantly lower in lung cancer samples, as compared with adjacent non-tumor lung tissues (P < 0.001)." (PMID 24981056, 2014). "It has been reported that the USP33/SLIT2/ROBO1 signalling pathway inhibits the migration of cancer cells; therefore, we hypothesised that miR-365a-3p downregulates this pathway to promote lung cancer progression." (PMID 29743814, 2018). "We identified seven proteins (Amph, Dok3, Ddx17, Mbip, Rim2, Skap2, TACC3, and Usp33) that are predicted to be EGFR interaction partners and/or share interaction partners within the EGFR pathway, and three of these (Amph, Rim2, and TACC3) show increased expression levels in lung cancer." (PMID 27956147, 2017).
hepatocellular carcinoma (6 papers, 2018 to 2025). A malignant tumor that arises from hepatocytes. "Previous reports have shown that USP33 promotes metastasis in hepatocellular carcinoma by deubiquitinating transcription factor (SP1) and upregulating cell-surface receptor c-mesenchymal–epithelial transition factor (c-MET) expression." (PMID 40695806, 2025). "For example, in hepatocellular carcinoma (HCC), the deubiquitinase USP33 stabilizes Sp1, leading to increased c-Met expression and enhanced HCC metastasis." (PMID 40125551, 2025). "In contrary, an oncogenic role of USP33 was also observed in hepatocellular carcinoma (HCC) and prostate cancer cells." (PMID 39694539, 2025). "In hepatocellular carcinoma USP33 functioned as an oncogene, the expression of USP33 was upregulated in HCC patients and the USP33 expression was negatively correlated with the prognosis of HCC patients." (PMID 37322017, 2023).
prostate carcinoma (6 papers, 2021 to 2025). A carcinoma that arises from epithelial cells of the prostate gland. "In prostate cancer, USP33 overexpression prevents the degradation of the phosphatase dual-specificity phosphatase 1 (DUSP1), impairing c-jun N-terminal kinase (JNK) activation and apoptosis, which contributes to docetaxel resistance." (PMID 40695806, 2025). "Collectively, circ_0057558 gives an impetus to cell proliferation and cell cycle control in prostate cancer cell lines by sponging miR-206 and positively regulating the transcription of the miR-206 target gene USP33." (PMID 33718387, 2021). "Collectively, the current study shows that circ_0057558 gives an impetus to cell proliferation and cell cycle transition in prostate cancer cell lines by sponging miR-206 and positively regulating the transcription of the miR-206 target gene USP33." (PMID 33718387, 2021). "Moreover, USP33 was reported to be overexpressed in prostate cancer cells and tissues and functioned as an oncogene of prostate cancer." (PMID 37322017, 2023). "All these findings propose that miR-206/USP33/c-Myc axis may mediate the oncogenic role of circ_0057558 in prostate cancer." (PMID 33718387, 2021). "Together, the findings proved that USP33 was a direct target gene of miR-206 in prostate cancer." (PMID 33718387, 2021). "Then USP33 mRNA expression was assessed in prostate cancer specimens and controls." (PMID 33718387, 2021). "USP33 could inhibit docetaxel-induced apoptosis of prostate cancer cells, including androgen-independent prostate cancer cells, mechanistically, USP33 could inhibit the Lys48 (K48)-linked polyubiquitination of DUSP1 which led to impaired JNK activation and apoptosis in prostate cancer." (PMID 37322017, 2023). "Moreover, qRT-PCR revealed that USP33 was upregulated in prostate cancer tissues." (PMID 33718387, 2021). "USP33 directly bound dual specificity protein phosphatase 1 (DUSP1) and reduced its ubiquitination, thereby impairing JNK activation and apoptosis in prostate cancer." (PMID 39694539, 2025). "The interaction between USP33 and SELENBP1 was detected by a two-hybrid assay in human prostate cancer cells, indicating SELENBP1 may play a role in epigenetics regulation." (PMID 36386843, 2022). "USP33 mRNA expression was significantly increased in prostate cancer tissues compared to non-cancerous tissue samples." (PMID 33718387, 2021). "USP33 mRNA expression in prostate cancer tissues has negative correlation with miR-206 expression and positive correlation with circ_0057558 expression." (PMID 33718387, 2021). "USP33 mRNA expression has negative correlation with miR-206 expression and positive correlation with circ_0057558 expression in prostate cancer tissues." (PMID 33718387, 2021). "Moreover, USP33 mRNA expression in prostate cancer tissues showed a negative correlation with miR-206 expression and a positive correlation with circ_0057558 expression." (PMID 33718387, 2021).
breast carcinoma (5 papers, 2014 to 2025). "In breast cancer cells, USP33 acts to redistribute Robo1 from the intracellular compartment to cell surface without affecting the total level of Robo1 protein." (PMID 24981056, 2014). "Our previous study has demonstrated that Slit inhibits breast cancer cell migration in a mechanism dependent on USP33." (PMID 24981056, 2014). "Our previous work indicates that USP33 is required for Slit signaling in breast cancer." (PMID 24981056, 2014). "Similarly, lower expression of USP33 correlated with poorer survival in a range of other types of cancers, including breast cancer (BRCA), melanoma (SKCM) and acute myeloid leukemia (AML)." (PMID 24981056, 2014). "Additionally, USP33 is required for Slit signaling to inhibit breast cancer cell migration." (PMID 40695806, 2025).
colorectal cancer (5 papers, 2015 to 2026). A primary or metastatic malignant neoplasm that affects the colon or rectum. "In colorectal cancer, the USP33 expression was downregulated and related to tumor grade, lymph node metastasis, and prognosis." (PMID 36582601, 2022). "In this study, we examined PD-L1 expression in various types of immune cells in human colorectal cancer in connection to cancer progression-specific USPs, including USP10, USP12, USP14, USP18, USP32, USP33, and USP39." (PMID 41356798, 2026). "Moreover, studies have shown that USP7, USP10, USP33, and USP46 are all involved in the progression of colorectal cancer." (PMID 37371055, 2023).